PRTN3 (proteinase 3)
Description:
Serine protease that degrades elastin, fibronectin, laminin, vitronectin, and collagen types I, III, and IV (in vitro). By cleaving and activating receptor F2RL1/PAR-2, enhances endothelial cell barrier function and thus vascular integrity during neutrophil transendothelial migration. Plays a role in neutrophil transendothelial migration, probably when associated with CD177. Triggers inflammatory processes in neutrophils by interacting with ADGRG3 upstream of F2RL1/PAR2 activation.
Synonyms: PR-3; PR3; NP-4; MBN; ACPA; C-ANCA; AGP7; MBT; P29; CANCA; NP4
Tractability: Small molecule: a high-quality ligand is known; it has a high-quality binding pocket. Antibody: UniProt places it where antibodies can reach, with high confidence; its Gene Ontology location is reachable by antibodies, with high confidence; UniProt predicts a signal peptide or a membrane-spanning region. PROTAC: a small molecule that binds it is known.
Target class: Serine protease; Enzyme; Serine protease PA clan; Serine protease S1A subfamily; Protease
Gene: Protein-coding gene on chromosome 19 (840,999 to 848,175, forward strand). Ensembl gene ENSG00000196415.
Subcellular location: Cytoplasmic granule; Secreted; Cell membrane; Membrane raft
Subcellular location (Human Protein Atlas): Cytosol; Vesicles; Predicted to be secreted
Pathways (Reactome):
Immune System: Antimicrobial peptides; Neutrophil degranulation; Other interleukin signaling
Hemostasis: Regulation of clotting cascade
Gene Ontology:
Molecular function: enzyme binding; protein binding; serine-type endopeptidase activity; signaling receptor binding; serine-type peptidase activity
Biological process: cell-cell junction maintenance; mature conventional dendritic cell differentiation; membrane protein ectodomain proteolysis; negative regulation of phagocytosis; neutrophil extravasation; positive regulation of GTPase activity; proteolysis; antimicrobial humoral response; positive regulation of cell population proliferation
Cellular component: azurophil granule lumen; cytosol; extracellular exosome; extracellular matrix; extracellular region; membrane raft; plasma membrane; plasma membrane raft
Genetic constraint (gnomAD): Loss-of-function variants: 22 observed, 15.42 expected, observed/expected ratio (o/e) 1.43, 90% interval 1.01 to 1.88. The synonymous counts are far from expectation, so gnomAD's model fits this gene poorly and the ratio says little. Missense variants: 378 observed, 296.45 expected, observed/expected ratio (o/e) 1.28, 90% interval 1.17 to 1.39. Synonymous variants: 173 observed, 124.18 expected, observed/expected ratio (o/e) 1.39, 90% interval 1.23 to 1.58.
Homologues: Orthologues: chimpanzee PRTN3 (97% identical), pig PRTN3 (72% identical), mouse Prtn3 (64% identical), rat Prtn3 (63% identical), macaque PRTN3 (59% identical), tropical clawed frog prtn3 (45% identical). Paralogues in human: ELANE (53% identical), CELA2A (36% identical), CELA3B (35% identical), CELA3A (35% identical), CELA2B (34% identical), CELA1 (31% identical).
Diseases named in the same sentence as PRTN3 in open-access papers:
PRTN3 is named in the same sentence as 410 diseases in open-access papers, as found by Europe PMC text mining. Sharing a sentence is not in itself a finding about the gene and the disease. The quoted sentences say what the papers report.
vasculitis (285 papers, 2005 to 2026). "The patient had a history of chronic limb ischemia of the left upper extremity due to proteinase 3-specific antineutrophil cytoplasmic antibody (PR3-ANCA)-associated vasculitis." (PMID 40656149, 2025). "Anti-neutrophil cytoplasmic antibody (ANCA)-associated vasculitis is characterized by small vessel inflammation and the presence of autoantibodies against cytoplasmic proteases, most often proteinase-3 and myeloperoxidase." (PMID 35445945, 2022). "Contrastingly, myeloperoxidase (MPO) and proteinase 3 (PR3) antibodies are features of ANCA-associated vasculitis (granulomatosis with polyangiitis, microscopic polyangiitis, and eosinophilic granulomatosis with polyangiitis)." (PMID 36419545, 2022). "Human proteinase 3 (PR3) is an important autoantigen implicated in the genesis of c-Antineutrophil cytoplasmic antibodies (ANCA) associated vasculitis." (PMID 36846563, 2022). "Studies looking exclusively into cases of AAV differentiate between antimyeloperoxidase-associated vasculitis, usually pANCA-positive, and antiproteinase 3-associated vasculitis, a cANCA-positive condition." (PMID 34289006, 2022). "Our discovery cohort comprised 40 patients with systemic vasculitis (cohort 1), and emerged as part of investigation of expression of vasculitis-associated autoantigens (proteinase 3 (PR3), myeloperoxidase, and the associated alloantigen CD177)." (PMID 27227454, 2016). "Genetic factors are also different, because PR3-ANCA vasculitis is partnered with HLA-DP and the genes encoding PR3 (PRTN3) and antitrypsin (SERPINA1)." (PMID 26236499, 2015). "A 77-year-old man developed severe renal insufficiency due to proteinase 3 anti-neutrophil cytoplasmic antibody (PR3-ANCA)-associated vasculitis, and was started on hemodialysis (HD)." (PMID 28509286, 2013). "The vasculitis is associated with highly specific anti-neutrophil cytoplasmic autoantibodies to proteinase 3 (PR3-ANCA)." (PMID 22490506, 2012). "Animal model studies provided some evidence of a direct pathogenic effect of passively transferred MPO and proteinase 3-specific ANCAs in inducing pauci-immune glomerulonephritis and vasculitis." (PMID 23283308, 2008). "Indeed, prolonged infections have been associated with the development of antibodies specific to proteinase 3 and vasculitis development, but the bacterial components triggering the production of autoantibodies have not been described for this disease." (PMID 36846563, 2022). "Recent data suggest distinct pathogenic pathways for myeloperoxidase (MPO) and proteinase 3 (PR3) ANCA vasculitis, which could result in different modes of presentation and outcome, although overlapping features are not infrequent." (PMID 26123651, 2015). "The recently suggested distinct pathogenic pathways for myeloperoxidase (MPO) and proteinase 3 (PR3) anti-neutrophilic cytoplasmic antibodies (ANCA) associated vasculitis could result in different modes of presentation and outcome." (PMID 26123651, 2015). "Antineutrophil cytoplasmic antibody (ANCA) associated vasculitis is a multisystemic disease process often resulting in necrotizing arteritis, with immune complex deposits observed in small to medium-sized vessels, including ANCAs directed against proteinase 3 (PR3) and myeloperoxidase (MPO)." (PMID 35538584, 2022). "GPA is part of the ANCA‐associated vasculitis spectrum, most often associated with cytoplasmic ANCA against proteinase‐3 (c‐ANCA/PR3)." (PMID 41573623, 2026). "Diagnoses considered were atypical vasculitis versus recurrent infection with underlying immune deficiency, supported by the positive c-ANCA (anti-proteinase 3) and p-ANCA (anti-myeloperoxidase)." (PMID 40502912, 2025). "We present a case of proteinase 3 (PR3)-positive vasculitis with concurrent invasive aspergillosis in a 68-year-old male in whom both the clinical presentation and immunochemical picture were atypical." (PMID 39882203, 2025).
vasculitis (continued). "This suggests that the vasculitis risk allele not only increases PRTN3 transcription and PR3 plasma protein levels, but also changes the structural and granular properties of neutrophils." (PMID 37596262, 2023). "In ANCA-associated vasculitis, the presence of proteinase 3, MPO and lysosome‐associated membrane protein 2 antibodies can stimulate neutrophils to release NETs, exacerbating the injury caused by vasculitis." (PMID 37478141, 2023). "There were ten cases with new-onset ANCA vasculitis, including 3 cases associated with proteinase 3 (PR3) and 7 cases of myeloperoxidase (MPO)-associated vasculitis, while six cases were ANCA vasculitis relapses." (PMID 36366292, 2022). "ANCAs directed against proteinase 3 (PR3) or myeloperoxidase (MPO) bind their cell surface-presented antigen, activate neutrophils, and cause vasculitis." (PMID 36125911, 2022). "There are many ANCA specificities in different autoimmune diseases but only myeloperoxidase (MPO) and proteinase 3 (PR3) that are expressed on the surface of primed neutrophils are major ANCA-antigens in vasculitis." (PMID 31616410, 2019). "Anti-neutrophil cytoplasmic antibody (ANCA) vasculitis is characterized by the presence of autoantibodies to myeloperoxidase and proteinase-3, which bind monocytes in addition to neutrophils." (PMID 28138552, 2017). "Granulomatosis with polyangiitis (GPA) is a small and medium-sized vessels vasculitis which is highly associated with positive anti-neutrophil cytoplasmic antibodies (ANCA), mainly with antibodies against proteinase 3 (PR3)." (PMID 27293945, 2016). "A panel of serological tests for vasculitis were checked and showed elevated titers of cANCA and anti-proteinase 3 antibodies." (PMID 19105841, 2008). "Extensive systemic evaluation, including autoimmune and vasculitis testing with antinuclear antibody, extractable nuclear antigen panel, complement levels, and antineutrophil cytoplasmic antibody testing with proteinase-3 and myeloperoxidase antibodies, was repeatedly unremarkable." (PMID 41930087, 2026). "Initially investigated for suspected lung malignancy due to her advancing age and history of non-Hodgkin’s lymphoma (in remission since 2017), the patient was diagnosed with proteinase 3 (PR3) anti-neutrophil cytoplasmic antibody (ANCA)-positive vasculitis and characteristic imaging findings." (PMID 41426880, 2025). "Furthermore, ANCA vasculitis can be classified into proteinase 3 (PR3-ANCA) and myeloperoxidase (MPO-ANCA) which are cytoplasmic antigens that are present at the surface of cytokine-stimulated leucocytes." (PMID 39310478, 2024). "For example, antibodies that recognize the neutrophil proteins proteinase 3 (PR3) and myeloperoxidase (MPO) are associated with vasculitis and have been shown to stabilize extruded chromatin content from neutrophils called neutrophil extracellular traps (NETs)." (PMID 38652559, 2024). "Anti-neutrophil cytoplasmic antibody (ANCA)-associated vasculitis (AAV) is a heterogeneous group of small vasculitis of unknown etiology, characterized by the presence of proteinase 3 (PR3) and myeloperoxidase (MPO) in the serum." (PMID 39726748, 2024). "In addition, our study identified two hub genes which work as autoantigens in anti-neutrophil cytoplasmic antibody (ANCA)-associated vasculitis abnormally elevated in active renal involvement patients, including MPO and PRTN3." (PMID 36530895, 2022). "Genome-wide association studies (GWAS) have shownd that HLA-DP (rs3117242) variants contribute to the pathogenesis of MPO-ANCA associated vasculitis, while PRTN3 (rs 62,132,295) variants might contribute to PR3-ANCA associated vasculitis." (PMID 30286799, 2018). "The second is anti-neutrophil cytoplasmic antibody (ANCA)-associated vasculitis attributed to the levamisole component, myeloperoxidase (MPO) and proteinase 3 (PR3) positive, whose main manifestations are typical cutaneous findings, arthralgias, otolaryngologic involvement, and agranulocytosis." (PMID 27824551, 2016).
vasculitis (continued). "We herein report the case of a HD patient with proteinase 3-ANCA (PR3-ANCA) associated vasculitis, in whom combined therapy with MZR and PSL successfully elicited the remission of alveolar hemorrhage, lowered the PR3-ANCA titer, and maintained disease remission." (PMID 28509286, 2013). "Anti-neutrophil cytoplasmic antibody (ANCA)-associated vasculitis is group of autoimmune diseases that affect small and medium-sized blood vessels and are characterized by the production of ANCA directed against proteinase 3 (PR3-ANCA) or myeloperoxidase (MPO-ANCA) by B cells." (PMID 39742256, 2024). "Additionally, a very similar model has independently been proposed to explain the etiology of anti-neutrophil cytoplasm antibody (ANCA) vasculitis as a result of the immune response to proteinase 3, collagen, and their complementary antigens, which include plasminogen." (PMID 37569555, 2023). "ANCA antibodies targeting neutrophil granule enzymes proteinase 3 (PR3) and myeloperoxidase (MPO) extend antibody-defined endophenotype concepts into vasculitis realms." (PMID 41562780, 2026). "Neutrophils expressing c-Kit exhibit enhanced surface expression of proteinase 3 (PR3), the target of anti-neutrophil cytoplasmic antibodies (ANCAs) in vasculitis." (PMID 40149573, 2025). "The immunopathology of ANCA vasculitis is in part driven by autoantibodies to two known autoantigens, myeloperoxidase (MPO) and proteinase 3 (PR3)." (PMID 39015144, 2024). "Anti-MPO and anti-proteinase 3 (PR3) antibodies can activate neutrophils in vitro, which is responsible for vasculitis." (PMID 39803122, 2024). "Proteinase 3 (PR3) is a neutrophil granulocyte enzyme and an autoantigen found in several forms of vasculitis." (PMID 36975370, 2023). "At the Nephrology Department, anti-proteinase 3 ANCA (PR3-ANCA) positivity (461 U) was detected, and urgent kidney biopsy showed pauci-immune, crescentic glomerulonephritis with the signs of vasculitis." (PMID 33832425, 2021). "The two main ANCA auto-antigens involved in the pathogenesis of vasculitis are myeloperoxidase (MPO-ANCA) and proteinase 3 (PR3-ANCA)." (PMID 34943555, 2021). "Chronic T cells activation promotes B cells secretion of antineutrophil cytoplasmic antibodies (ANCAs) targeting proteinase 3 (PR3) or myeloperoxidase (MPO) which trigger neutrophil activation and lead to vasculitis." (PMID 33287743, 2020). "Moreover, a transient positivity of anti-neutrophil cytoplasmic antibodies (ANCA), with anti-proteinase 3 or anti-myeloperoxidase specificity, has been reported in 10% of patients during acute PVB19 infection, and is a potential pitfall for the diagnosis of ANCA-associated vasculitis." (PMID 32646497, 2020). "In vasculitis, myeloperoxidase (MPO) and proteinase-3 (PR3), the two auto-antigens recognized by anti-neutrophil cytoplasm antibodies (ANCA), are, in fact, released from NETs21." (PMID 31138830, 2019). "None of the IBD and SpA patients recognized myeloperoxidase antigen, elastase, lactoferrin, proteinase 3, or cathepsin G, indicating that p-ANCA is a different antigen that is specifically recognized in vasculitis." (PMID 29213287, 2017). "Detailed clinical information, including Birmingham Vasculitis Activity Score (BVAS), incidence of lung involvement, anti-proteinase 3 (PR3) antibodies concentrations, and other laboratory data were collected in 38 GPA patients." (PMID 27127514, 2016). "The major target antigens in patients with vasculitis and glomerulonephritis are myeloperoxidase (MPO) and proteinase 3 (PR3)." (PMID 26688808, 2015). "The diagnosis is established based on clinical, radiological findings, presence of c-ANCA (by immunofluoresce), and anti-Proteinase 3 (PR3) antibodies by ELISA, supported by histological evidence of granulomas and vasculitis." (PMID 24707429, 2014).
vasculitis (continued). "Meanwhile, the prevalences of antibodies against the proteinase 3, cathepsin G, lactoferrin, HLE, and azurocidin were significantly higher in patients with PTU-induced vasculitis than those in patients with PTU-induced MPO-ANCA but without clinical vasculitis." (PMID 24252385, 2013). "Antineutrophil cytoplasmic antibody (ANCA)-associated vasculitis (AAV) is a group of complex autoimmune diseases characterized by the vasculitis, endothelial injury, and tissue damage as well as the presence of serum autoantibodies targeting myeloperoxidase (MPO-ANCA) or proteinase 3 (PR3-ANCA)." (PMID 38578316, 2024). "However, proteinase 3-ANCA (PR3-ANCA) and MPO-ANCA have been found in most vasculitis patients, both characteristic of AAV pathogenesis." (PMID 35409152, 2022). "In total, of five vasculitis patients, two had ANCA-negative eosinophilic granulomatosis with polyangiitis (EGPA) and three had granulomatosis with polyangiitis (GPA) with antibodies against proteinase-3." (PMID 36514177, 2022). "AAV = ANCA associated vasculitis, GPA = granulomatosis with polyangiitis, PR3 = Proteinase-3 ANCA, eGFR = estimated Glomerular Filtration Rate (CKD-EPI), ml/min/1.73 m2, BVAS = Birmingham Vasculitis Activity Score, RRT = Renal Replacement Therapy, 95% CI = 95% Confidence Interval." (PMID 37251362, 2022). "Vasculitis, a shared condition between fatal COVID-19 and vascular autoimmune diseases such as Anti-neutrophil cytoplasmic autoantibody (ANCA) vasculitis, is featured by elevation of MPO and PRTN3 levels." (PMID 34276672, 2021). "Antineutrophil cytoplasmic antibody (ANCA)-associated vasculitis (AAV) is a systemic autoimmune disorder involving a pauci-necrotizing small-sized vasculitis, in which ANCA targeting myeloperoxidase (MPO) and proteinase 3 (PR3) participate in the pathogenesis of the disease." (PMID 34950150, 2021). "This type of vasculitis may be myeloperoxidase (MPO) and proteinase 3 (PR3) positive, and its main manifestations are typical cutaneous findings, arthralgia, otolaryngologic involvement, and agranulocytosis." (PMID 27824551, 2016). "These diseases are characterized by the presence of ANCA which vary depending on the vasculitis type and whether they are directed against myeloperoxidase (MPO) or proteinase 3 (PR3)." (PMID 26236499, 2015). "Both myeloperoxidase (MPO) antineutrophil cytoplasmic antibody (ANCA) and proteinase 3 (PR3) ANCA levels were within normal reference ranges, suggesting no active vasculitis or ANCA-associated autoimmune disorder, ruling out a vasculitic cause for this presentation." (PMID 40718213, 2025). "ANCA directed against proteinase 3 (PR3) and myeloperoxidase (MPO) have the ability to activate neutrophils, increasing their ability to adhere to the endothelial cells, which in turn induces oxygen release and lithic enzymes that damage blood vessel walls, producing vasculitis." (PMID 33215484, 2020). "The excess of proteinase-3, not neutralized by AAT, could also play an important role in AAT deficiency subjects with antineutrophilic cytoplasmatic antibody C-ANCA positive vasculitis." (PMID 21486454, 2011). "Serologies to assess for vasculitis included negative anti-myeloperoxidase (MPO), anti-proteinase 3 (PR3), anti-glomerular basement membrane (GBM), and antistreptolysin antibodies." (PMID 39726463, 2024). "For the AAV group, neither myeloperoxidase (MPO) or proteinase-3 (PR3) ANCA levels (rho = 0.09, p = 0.63 and rho = −0.035, p = 0.85, respectively) nor the Birmingham Vasculitis Activity Score (BVAS) (rho = 0.017, p = 0.93) significantly correlated with anti-oxLDL antibody levels." (PMID 37240332, 2023).